DLAT (dihydrolipoamide S-acetyltransferase)
Diseases named in the same sentence as DLAT in open-access papers (continued):
Sharing a sentence is not in itself a finding about the gene and the disease.
ulcerative colitis (2 papers, 2017 to 2022). An inflammatory bowel disease involving the mucosal surface of the large intestine and rectum. "Cuproptosis-related regulators exhibited extensive differential expression in Crohn’s Disease (CD), Ulcerative Colitis (UC), Celiac Disease (CEL), and IBD-induced cancer (IBD-CA) that share common differential genes (PDHA1, DBT, DLAT, LIAS)." (PMID 36405733, 2022).
acute myocardial infarction (1 paper, 2024). Necrosis of the myocardium, as a result of interruption of the blood supply to the area. "In contrast, patients with acute myocardial infarction exhibit decreased levels of LIAS, PDHB, LIPT1, DLAT, and GLS, along with increased MTF1 levels." (PMID 39360273, 2024).
Alzheimer disease (1 paper, 2024). A progressive, neurodegenerative disease characterized by loss of function and death of nerve cells in several areas of the brain leading to loss of cognitive function such as memory and language. "This study investigates the interaction between pyruvate kinase M2 (PKM2) and dihydrolipoamide S‐acetyltransferase (DLAT), particularly focusing on copper‐induced neuronal death in Alzheimer's disease." (PMID 39428563, 2024).
Cerebral ischemia (1 paper, 2024). Restriction of arterial blood supply to the brain associated with insufficient oxygenation to support the metabolic requirements of the tissue. "The present study also identified DLAT as one of the hub genes responsible for cuproptosis after cerebral ischemia." (PMID 39360273, 2024). "Eight hub genes (FDX1, LIPT1, LIAS, DLD, PDHA1, DLAT, PDHB, and GLS) were identified as potential core targets of cerebral ischemia." (PMID 39360273, 2024).
cervical cancer (1 paper, 2021). A primary or metastatic malignant neoplasm involving the cervix. "Co-IP assays with an anti-STAT5A antibody demonstrated that endogenous STAT5A interacted with multiple PDC subunits, including PDHA1, PHDB, DLD, and DLAT in 293T, HeLa (a human cervical cancer cell line), MIHA (a human hepatocyte), and primary mouse hepatocytes." (PMID 34148062, 2021).
cognitive decline (1 paper, 2024). "In 5xFAD mice, increased DLAT expression was linked to hippocampal damage and cognitive decline." (PMID 39428563, 2024).
Cognitive impairment (1 paper, 2024). Abnormal cognition is characterized by deficits in thinking, reasoning, or remembering. "The results indicate that extracellular vesicles derived from microglial cells mediate the transfer of sh‐PKM, downregulate DLAT expression, and inhibit copper‐induced cell death, thereby alleviating cognitive impairment in AD mice." (PMID 39428563, 2024). "By analyzing expression profile data related to AD, this study reveals upregulation of DLAT in AD, and knocking down DLAT can ameliorate cognitive impairments in an AD mouse model." (PMID 39428563, 2024). "The results of the Morris water maze experiment showed that compared to the 5xFAD + sh‐NC group, the escape latency decreased, and the time spent crossing the platform increased in the 5xFAD + sh‐DLAT group, indicating that knocking down DLAT alleviated cognitive impairment in AD mice." (PMID 39428563, 2024).
lymph node metastasis (1 paper, 2022). "ATP7A (P = 0.007), LIPT1 (P = 0.009), DLAT (P = 0.006) and NDOR1 (P = 0.039) expression were remarkably interrelated to lymph node metastasis (N classification)." (PMID 36313717, 2022).
male infertility (1 paper, 2023). The inability of the male to effect fertilization of an ovum after a specified period of unprotected intercourse. "Among these were well-studied protein biomarkers for male infertility such as IDH3A, GAPDHS, FH, and DLAT." (PMID 36509450, 2023).
nonalcoholic fatty liver disease (1 paper, 2024). "The results revealed significant correlations between dihydrolipoamide s-acetyltransferase (DLAT), dialectical behavior therapy (DBT), metal regulatory transcription factor 1 (MTF1), nonalcoholic fatty liver disease (NFE2L2), and developmental language disorder (DLD)." (PMID 38673957, 2024).
paraganglioma (1 paper, 2023). A benign or malignant neoplasm arising from paraganglia located along the sympathetic or parasympathetic nerves. "On the contrary, we found relatively low DNA methylation levels of DLAT in KIRC, LIHC, LUAD, pheochromocytoma and paraganglioma (PCPG), and sarcoma (SARC)." (PMID 36949759, 2023).
pulmonary fibrosis (1 paper, 2023). Chronic progressive interstitial lung disorder characterized by the replacement of the lung tissue by connective tissue, leading to progressive dyspnea, respiratory failure, or right heart failure. "It’s reported that the CRGs, such as FDX1, LIAS, DLD, PDHA1, PDHB, DLAT, and LIPT1, were down-regulated in the lung tissues of pulmonary fibrosis mouse model, and the same results were obtained via analysis of lung tissues scRNA-seq data for human pulmonary fibrosis." (PMID 37266442, 2023).
rubella (1 paper, 2023). A viral infection caused by the rubella virus. "In rubella, including five in whole blood (JAGN1, RRP12, RP11-452K12.7, CASP7, and AP3S2), four in the lung tissue (IL17RC, FAM86HP, AMACR, and RRP12), and four in the transformed fibroblast cells (PPP2R1B, C11orf1, DLAT, and TMEM117)." (PMID 37020999, 2023). "Similarly, in transformed fibroblast cells, we found PPP2R1B (padjusted = 0.022), C11orf1 (padjusted = 0.029), DLAT (padjusted = 0.045), and TMEM117 (padjusted = 0.046) as rubella-related genes." (PMID 37020999, 2023).
TCA cycle disorders (1 paper, 2025). "In summary, this study is the first to show that the FDX1-LIPT1-DLAT ternary complex can exacerbate TCA cycle disorders by inhibiting DLAT activation, that the opening and closing of the mPTP can regulate cuproptosis, and that circKIAA1797 can regulate cuproptosis through these two pathways." (PMID 40176113, 2025).
temporal lobe epilepsy (1 paper, 2024). A localization-related (focal) form of epilepsy characterized by recurrent seizures that arise from foci within the temporal lobe, most commonly from its mesial aspect. "Noteworthily, proteins such as ATP6V1A, DLAT, and HSP70 are expressed in the hippocampus of patients with temporal lobe epilepsy." (PMID 39360273, 2024).
tumor (93 papers, 2020 to 2026). "We exhibited that DLAT expression was positively associated with immune checkpoint genes in the majority of tumor types including GBMLGG and LGG." (PMID 39574473, 2024). "Several other studies have found that FDX1 and DLAT are associated with tumor progression." (PMID 37745716, 2023). "Notably, the high-risk group presented overexpression of three cuproptosis biomarkers: CDKN2A, DLD, and DLAT; moreover, tumor tissues of this group have more tumor mutation burden and less immune cell infiltration." (PMID 36003780, 2022). "Surprisingly, IDH2R140Q mutation changed the expression patterns of cupropotosis-associated genes, including FDX1, LIAS, LIPT1, DLD, DLAT, and PDHA1, which indicated that the sensitivity of tumor cells to cuproptosis depends on the types of genetic mutations." (PMID 40384935, 2025). "The high basal levels of PDHX acetylation led to the observation that PDHX-WT and PDHX-K488Q exhibit similar effects on the interaction between PDHX and DLAT, as well as on tumor proliferation." (PMID 39311688, 2025). "A novel prognostic risk model based on four CRGs (ORC1, PTTG1, DLAT, PDHB) was developed to stratify COAD patients into high-risk and low-risk groups, assessing overall survival, tumor microenvironment, and mutational landscape differences." (PMID 40276654, 2025). "Firstly, Western blot analysis revealed that compared to the Vector+PBS + PBS group, the RPS27-RPS24 + PBS + PBS group of mice showed a significant increase in the expression levels of RPS27-RPS24, GLS, FDX1, LIAS, and Lipoy-DLAT proteins in tumor tissues." (PMID 40280903, 2025). "Although elevated levels of Cu2+ are found in multiple tumor tissues and serum, key cuproptosis genes, includingFDX1,SDHB,DLAT, andDLST, are downregulated in tumor tissues." (PMID 40692442, 2025). "DLAT expression was lower in BC tumor tissues than in normal tissues at both the transcriptional and protein levels." (PMID 39460738, 2024). "Differential expression between normal tissues and BRCA tissues at each tumor stage was found in almost all cuproptosis-associated genes; however, only LIPT1, DLAT, PDHA1, and CDKN2A were differentially expressed among tumor stages." (PMID 39432636, 2024). "DLAT also functions as an acetyltransferase necessary for 6PGD lysine acetylation, which is of vital importance for tumor growth." (PMID 38722401, 2024). "An examination of mRNA transcriptome data from BC in The Cancer Genome Atlas (TCGA) revealed that DLAT transcript levels were reduced in tumor tissues compared to normal tissues." (PMID 39460738, 2024). "The results indicate that the average expression of DLAT at the tissue level was higher in the tumor group than in the normal group, and the difference between the two groups was statistically significant (p < 0.001)." (PMID 39031012, 2024). "The impact of the mitochondria‐dependent energy metabolizing enzyme DLAT, which related cuproptosis, on the energy metabolism of tumor cells and its potential involvement as a therapeutic target in the immunotherapy of tumors remained to be elucidated." (PMID 39031012, 2024). "Future research should explore other potential CRGs related to cuproptosis, investigate the functional roles of the four CRGs, especially DLAT, in HER-2-positive BRCA, and examine DLAT’s impact on anti-tumor immunity in these patients." (PMID 39867656, 2024). "Increased expression of DLAT leads tumor cells to be more resistant to many kinds of compounds, including PI3Kβ inhibitors, PKC inhibitors, HSP90 inhibitors, and MEK inhibitors." (PMID 39574473, 2024). "Investigation into cell proliferation, migration, and invasion in TNBC cell lines revealed that upregulation of DLAT exhibited tumor-promoting characteristics, whereas downregulation of DLAT demonstrated tumor-suppressor functions." (PMID 39460738, 2024).
tumor (continued). "Further, the expression of DLAT was also confirmed to be correlated with the tumor microenvironment and diverse infiltration of immune cells, especially tumor-associated macrophages (TAMs)." (PMID 37199628, 2023). "DLAT and its related genes were mainly involved in cell metabolism, tumor progression and immune regulation." (PMID 37828099, 2023). "Functional enrichment analyses indicated that the basic function of DLAT is closely related to metabolism, and multiple tumor-promoting and immune response-related pathways were enriched in DLAT-high PAAD samples." (PMID 36975441, 2023). "The IHC result showed the expression of DLAT was significantly higher in HCC than in their corresponding adjacent non-tumor tissues." (PMID 36845390, 2023). "The expression of DLAT in tumor tissues is significantly higher than that in paired adjacent nontumor tissues." (PMID 36975441, 2023). "In contrast, another gene we focused on, DLAT, is likely to activate anti-tumor immunity by inducing an increase in CD8-GZMK T cells." (PMID 38078879, 2023). "Our results, based on the TCGA and ArrayExpress databases, showed that patients with high DLAT expression had better OS, which indicated that DLAT functions as a tumor suppressor (P< .05)." (PMID 37938155, 2023). "Then, we isolated proteins from four pairs of tumor and adjacent tissues and verified the high expression of DLAT in PAAD at the protein level." (PMID 36975441, 2023). "First, the IHC results showed higher expression of COX17 and lower expression of DLAT within tumor tissues than normal tissues." (PMID 38078879, 2023). "The results exhibited that DLAT mRNA was significantly increased in tumor cell lines compared to normal cell line." (PMID 37330494, 2023). "The PDAC patients with higher expression levels of PDHA1, LIPT1, LIAS, and DLD, or lower expression levels of DLAT, in their tumor tissues had a better prognosis than their counterparts (p < 0.05)." (PMID 36826087, 2023). "We found that the expression of GCSH and DLAT was much higher in tumor tissues than in normal tissues in LUAD." (PMID 36353226, 2022). "Meanwhile, a large majority of cuproptosis-associated genes including FDX1, LIAS, DLD, DLAT, PDHA1, and GLS, were significantly associated with the tumor microenvironment (immune, stromal, and estimate scores) (p < 0.05)." (PMID 36105090, 2022). "Cu transporter-related genes including ATP7A, SLC31A1, and TCA-related genes including DBT, DLST, and DLAT are differentially expressed between normal and tumor samples." (PMID 36438201, 2022). "It was worth mentioning that five of them were downregulated in tumor samples, including DLAT, MTF1, PDZD4, FDX1, and RPS25, and the rest of the genes were all upregulated." (PMID 36010978, 2022). "Similarly, key molecules of cuproptosis, such as FDX1 and DLAT, have been shown to function as tumor suppressors in GI tumors like HCC, and activating this pathway can significantly reduce tumor cell viability." (PMID 41201667, 2025). "Interestingly, we found that 3D tumor cells exhibited the oligomerization of dihydrolipoamide S-acetyltransferase (DLAT), a characteristic of cuproptosis whereas 2D tumor cells did not." (PMID 40050422, 2025). "In general, these results suggested that DLAT might regulate immune cell infiltration and the immune pathways in most tumor types." (PMID 39574473, 2024). "In addition, the aggregation of dihydrolipoamide S‐acetyltransferase (DLAT) protein can be observed in tumor tissues of mice treated with Cu(I) NP." (PMID 38269649, 2024). "In addition, the released Cu ions not only realized the cascade amplification of ROS generation through Cu+‐mediated Fenton‐like reaction, but also triggered tumor‐specific cuproptosis through Cu+‐induced DLAT oligomerization and mitochondrial dysfunction." (PMID 39331855, 2024). "Our study is the first to reveal the tumor-promoting role of DLAT in TNBC." (PMID 39460738, 2024).
tumor (continued). "Notably, the rapid accumulation of Cu+ and ES in tumor cells induced the aggregation of lipoylated dihydrolipoamide S-acetyltransferase (DLAT) and the downregulation of Fe‒S cluster proteins, ultimately leading to cuproptosis." (PMID 39554839, 2024). "The tumor‐specific released Cu ions not only realized the cascade amplification of ROS generation through Cu+‐mediated Fenton‐like reaction, but also triggered cuproptosis through Cu+‐induced DLAT oligomerization and mitochondrial dysfunction." (PMID 39331855, 2024). "The role of DLAT in cancer may be involved in metabolic reprogramming and affects tumor growth and survival." (PMID 39031012, 2024). "Additionally, we identified a potential link between METTL3 and DLAT in cuproptosis‐related tumour development, providing a new strategy for cancer prevention and treatment." (PMID 38429907, 2024). "Additionally, DLAT expression was positively correlated with immune regulatory genes in many tumor types including GBMLGG and LGG." (PMID 39574473, 2024). "DLAT expression was high in the tubules of normal kidney tissues and low in those of tumor tissues." (PMID 37938155, 2023). "Therefore, in this study, we conducted a comprehensive investigation into the expression of DLAT and its prognostic implications, while also exploring its potential relationship with tumor immunity in the context of pan-cancer analysis." (PMID 37199628, 2023). "The mRNA expression of DLAT was significantly upregulated in tumor samples than in the normal ones." (PMID 36611155, 2023). "Therefore, the enzyme encoded by DLAT determines to a certain extent, whether the energy-supplying substances derived from glucose can smoothly enter the citric acid cycle-oxidative phosphorylation pathway for complete hydrolysis to generate energy or supply more synthetic lipids for tumor cells." (PMID 36117848, 2022). "Moreover, bioinformatics analysis showed that Sp1 expression levels were positively correlated with that of DLAT in tumor tissues in TCGA data set." (PMID 35869499, 2022). "Similarly, analyses of TCGA dataset also indicated that eIF4E expression levels were positively correlated with that of DLAT in NSCLC tumor tissues." (PMID 35869499, 2022). "Therefore, taking advantage of the upregulated expression of DLAT, supported by glycolysis inhibitors, and using copper carriers to induce cuproptosis in GC cells may become a potentially promising tumor therapeutic strategy." (PMID 39031012, 2024). "Additionally, we found that DLAT expression was significantly higher in the high METTL3 expression group than in the low expression group, highlighting the potential association between these two genes in cuproptosis‐related tumour development." (PMID 38429907, 2024). "In conclusion, DLAT may promote the tumor progression through these tumor-related pathways." (PMID 37330494, 2023). "Furthermore, high expression of DLAT was significantly associated with tumor size and advanced TNM/BCLC stage, suggesting that DLAT may promote HCC progression." (PMID 37949877, 2023). "Functional enrichment analysis also revealed that DLAT was engaged in cell division, indicating that DLAT might promote tumor progression by activating proliferative processes, such as mismatch repair, DNA replication, nucleotide excision repair, and cell cycle." (PMID 37330494, 2023). "Hence, FDX1, DLD, DLAT, and CDKN2A may play important roles in immune interactions and may be associated with tumor immune evasion." (PMID 36531222, 2022). "Mechanistic studies confirmed that this formulation specifically accumulates copper ions within tumor cells, upregulates FDX1, promotes DLAT oligomerization, and induces mitochondrial dysfunction, thereby driving copper death." (PMID 41599733, 2026). "Paired comparisons further confirmed the upregulation of FDX1, DLAT, PDHA1, GLS, and CDKN2A in tumor samples." (PMID 40410601, 2025).